CKAP2L (cytoskeleton associated protein 2L)
Diseases named in the same sentence as CKAP2L in open-access papers (continued):
Sharing a sentence is not in itself a finding about the gene and the disease.
prostate carcinoma (4 papers, 2021 to 2025). A carcinoma that arises from epithelial cells of the prostate gland. "Taken together, CKAP2L plays a carcinogenic role in prostate cancer by regulates the expression of cycle-associated proteins." (PMID 35715760, 2022). "In addition, CKAP2L is reportedly involved in the occurrence and development of other malignant tumors, such as breast and prostate cancers, and is associated with poor prognosis of these cancers." (PMID 34631884, 2021). "To further investigate the biological function of CKAP2L in human prostate cancer cell lines, we performed sh-RNA mediated CKAP2L stable knockdown in the highest expression of CKAP2L prostate cancer cell line." (PMID 35715760, 2022). "In the present study, we elucidated the expression of CKAP2L and its relation to the cell cycle signaling pathway demonstrated the CKAP2L regulation by miRNA in prostate cancer." (PMID 35715760, 2022). "In this study, we aim to delineate the prominent dysregulated expression of CKAP2L and comprehensively reveal its deregulation in prostate cancer." (PMID 35715760, 2022). "Expanded the function of CKAP2L in prostate cancer by activation of the process of cell cycle and mitosis." (PMID 35715760, 2022). "Consistent with the results of immunohistochemistry, western blot of samples from prostate cancer patients showed that CKAP2L expression remarkably upregulated in protein-level with the prostate cancer progression." (PMID 35715760, 2022). "CKAP2L expression was examined in the normal and tumor tissues of prostate cancer patients with RT-QPCR and Western blot." (PMID 35715760, 2022). "In summary, our study revealed that overexpression of miR-326 can inhibit cell proliferation, migration and invasion in prostate cancer cell line by regulating CKAP2L expression, which can be further investigated as a potential treatment target and a novel diagnosis marker." (PMID 35715760, 2022). "Firstly, we verified the high expression of CKAP2L in prostate cancer tissues and cell lines." (PMID 35715760, 2022). "This indicated that CKAP2L might play a pivotal role in prostate cancer progression." (PMID 35715760, 2022). "Therefore, targeting CKAP2L by delivering miR-326 might be a feasible treatment to control prostate cancer progression." (PMID 35715760, 2022).
esophageal squamous cell carcinoma (3 papers, 2022 to 2024). Esophageal squamous cell carcinoma (ESCC) is a type of esophageal carcinoma (EC) that can affect any part of the esophagus, but is usually located in the upper or middle third. "A separate group of researchers reported that siRNA‐mediated depletion of CKAP2L in esophageal squamous cell carcinoma cells in culture increases the percentage of cells at the G2/M phase." (PMID 39073037, 2024).
hepatocellular carcinoma (3 papers, 2021 to 2024). A malignant tumor that arises from hepatocytes. "For example, Wang indicated that abnormal expression of CKAP2L was highly associated with poor prognosis of hepatocellular carcinoma (HCC) and over-expression of CKAP2L promoted migration and invasion in HCC cells." (PMID 36090903, 2022). "Moreover, Wang and He reported that increased expression of CKAP2L in hepatocellular carcinoma (HCC) cells promoted their migration and invasion, which was associated with poor prognosis of HCC." (PMID 34631884, 2021).
microcephaly (3 papers, 2016 to 2025). A congenital or acquired developmental disorder in which the circumference of the head is smaller than normal for the person's age and sex. "Loss of function mutations in CKAP2L associated with platelet traits cause the autosomal-recessive Filippi syndrome characterized by microcephaly, pre-, and post-natal growth failure, although case series do not describe hematological abnormalities." (PMID 27863252, 2016).
colorectal cancer (2 papers, 2022 to 2025). A primary or metastatic malignant neoplasm that affects the colon or rectum. "In addition, CKAP2L has been reported to be associated with disease progression and prognosis in a variety of tumors, including non-small-cell lung cancer, glioblastoma, hepatocellular carcinoma, and colorectal cancer." (PMID 36699449, 2022).
brain tumor (1 paper, 2020). "To further support the proposal that the decrease of cell number was due to the decline of proliferation ability, we looked at the association of the CKAP2L versus two common proliferation biomarkers in the TCGA and CGGA datasets, including MKI67 and MCM6, often used in brain tumor studies." (PMID 33375517, 2020). "To further investigate the relations between the cell decrease and proliferation ability, we looked at the association of the CKAP2L versus the commonly used proliferation biomarkers in the TCGA dataset, including MKI67 and MCM6 expression, which have been used in other brain tumor studies." (PMID 33375517, 2020).
COVID-19 (1 paper, 2022). A disease caused by infection with severe acute respiratory syndrome coronavirus 2. "Upstream regulator analysis identified five key regulators after exposure to COVID-19 in our study, one phosphatase (PDCD1), 3 transcriptional regulators (E2F3, NUPR1 and LARP1) and one mitotic spindle protein (CKAP2L)." (PMID 35547542, 2022).
neuroblastoma (1 paper, 2024). Neuroblastoma (NB) is the most common solid, extracranial childhood tumor. "The authors also reported that overexpression of Ckap2l in HEK293 cells and a neuroblastoma cell line results in excessive stabilization of microtubules and aberrant mitotic spindle formation." (PMID 39073037, 2024).
cancer (22 papers, 2020 to 2026). A tumor composed of atypical neoplastic, often pleomorphic cells that invade other tissues. "CKAP2L is associated with a poor prognosis, with high expression associated with advanced cancer stages and metastases." (PMID 40722386, 2025). "In this study, we comprehensively analyzed the expression of CKAP2L and its association with prognosis, chemotherapy and tumor immunity at the pan-cancer level by different databases, as well as partially validated our findings through in vitro experiments." (PMID 37225919, 2023). "CKAP2L (Cytoskeleton Associated Protein 2 Like) plays a newish role in cancer progression through activation of the process of cell cycle and mitosis." (PMID 35715760, 2022). "CKAP2L (cytoskeleton‐associated protein 2‐like) is a relatively new mitotic spindle‐associated protein, associated with neural progenitors as well as various cancers." (PMID 39073037, 2024). "In addition, ANLN expression was strongly associated with that of DEPDC, KIF14, KIF23, RACGAP1, and CKAP2L genes across cancers." (PMID 35340220, 2022). "CKAP2L mutation is related to defects in the spindle tissue, including mitotic spindle defects, chromosome hysteresis, and other mitotic instability characteristics, that are involved in the formation and development of cancer." (PMID 34631884, 2021). "Upregulation of DAP3 and CKAP2L are also known oncogenes that promote cancer development and resistance to radiation." (PMID 40135438, 2025). "In cancer literature, an overwhelming number of studies found that various types of human cancer exhibit an elevated level of CKAP2L expression, which often correlates with their poor prognosis." (PMID 39073037, 2024). "Various human cancer cell lines, including those originating from the lung, colon, and liver, were examined for CKAP2L protein expression using a CKAP2L‐specific antibody." (PMID 39073037, 2024). "In conclusion, CKAP2L can be used as a potential predictor of tumor prognosis and cancer therapy, providing immune-based antitumor strategies targeting CKAP2L." (PMID 37225919, 2023). "The results indicate that CKAP2L is a pro-cancer gene that serves as a potential biomarker for predicting patient outcomes." (PMID 37225919, 2023). "CKAP2L expression was related to the tumor stage in some cancers and increased with tumor stages in the ACC, BRCA, KICH, KIRC, KIRP, LUAD and THCA groups." (PMID 37225919, 2023). "According to the TCGA database, the activity of CKAP2L was elevated in 21 cancers, which was nearly consistent with the results of CKAP2L expression levels." (PMID 37225919, 2023). "TMB and MSI were potential predictive markers for immunotherapy, CKAP2L was positively correlated with TMB and MSI in most type cancers, indicating that patients with elevated CKAP2L expression in these tumors responded better to immunotherapy." (PMID 37225919, 2023). "Since there were few studies of CKAP2L on tumor immunity, this paper comprehensively analyzed the correlation between CKAP2L expression and tumor immunity at the pan-cancer level." (PMID 37225919, 2023). "CKAP2L mRNA expression levels were analyzed in TCGA with Timer to investigate CKAP2L expression over a cancer wide range." (PMID 35715760, 2022). "Recent studies have revealed that CKAP2L, an important oncogene, is involved in the biological behavior of many malignant tumors." (PMID 36090903, 2022). "A large body of literature has confirmed that CKAP2L is involved in regulating many types of malignant tumors, promoting the proliferation of tumor cells, and shortening the survival time of patients." (PMID 34631884, 2021). "Another notable example was CKAP2L, which clusters together with several genes identified from referencing of our immunopeptidomics data, including BIRC5, BRCA2, and CENPF, forming a cluster of genes associated with cell proliferation across cancers." (PMID 41477871, 2026).
cancer (continued). "Aberrant expression of CKAP2L may lead to the reorganization of the cytoskeleton, thereby enhancing the invasion ability of cancer." (PMID 40062654, 2025). "Knockdown of CKAP2L in various cancer cell lines has been shown to result in a G2/M arrest and retardation of the growth and migratory potential of the cancer cells, highlighting the potential role of CKAP2L in cancer cell growth and metastasis." (PMID 39073037, 2024). "CKAP2L protein was detectable in all human cancer cell lines we tested." (PMID 39073037, 2024). "For instance, the elevated expression of CKAP2L in various types of human cancer may reflect the high rate of cell proliferation which is inherent in malignant tissues." (PMID 39073037, 2024). "We speculate that the level of the G2/M phase markers, such as CKAP2L, reflect the overall cell proliferative rate and, thus, correlates with the “aggressiveness” of the cancer." (PMID 39073037, 2024). "Based on this, we speculate that excessive overexpression of CKAP2L is detrimental not only to normal cells but also to cancer cells." (PMID 39073037, 2024). "For this reason, it is currently unclear whether CKAP2L plays a bona fide, oncogenic, or tumor‐promoting role or simply correlates with the proliferative nature of cancer cells." (PMID 39073037, 2024). "Moreover, patients with higher CKAP2L expression had poorer OS in a comprehensive analysis of 33 cancers." (PMID 37225919, 2023). "Overall, we have investigated the function of CKAP2L at the pan-cancer level, which may offer evidence for its potential clinical application in the future." (PMID 37225919, 2023). "Our results show that CKAP2L was overexpressed and in high activity in most of the 33 tumors and its expression increases with tumor stage in 7 cancer types, suggesting that it may be an oncogene in most tumors." (PMID 37225919, 2023). "Similar to previous studies, we suggested that CKAP2L may contribute to tumor progression in KIRC by influencing the biological behavior of cancer cells through the cell cycle too." (PMID 37225919, 2023). "In the majority of cancers, CKAP2L expression and activity were markedly elevated." (PMID 37225919, 2023). "At the pan-cancer analysis level, we investigated whether CKAP2L expression is related to patient prognosis using data from the TCGA database." (PMID 37225919, 2023). "Related research reports that CKAP2L could activate the AKT/mTOR signaling pathway in cancer cells and promotes carcinogenesis." (PMID 36090903, 2022). "CKAP2L is accepted to promote cancer progression by involving in chromosomal instability." (PMID 35715760, 2022). "Furthermore, a large number of previous studies have confirmed that CKAP2L is involved in the regulation of a variety of cancers." (PMID 34631884, 2021). "Therefore, we hypothesize that CKAP2L may influence the biological behavior of cancer cells by regulating the cell cycle." (PMID 37225919, 2023). "Hence, according to the studies above and our results, CKAP2L might be a potential therapeutic target or another upstream regulator to mediate cyclin to control the cancer progression." (PMID 35715760, 2022). "The expression levels of CKAP2L in 33 tumors and normal tissues were analyzed by the TCGA database and TIMER2.0, finding that CKAP2L was differentially highly expressed in most cancers." (PMID 37225919, 2023). "Interestingly, this result, in contrast to the traditional chemotherapeutic agents, implies that immunotherapy may address drug insensitivity in patients with high CKAP2L expression, and CKAP2L may serve as a potential biomarker to guide the choice of cancer treatment modality." (PMID 37225919, 2023). "The correlation heatmap showed the top five genes (CCNA2, CKAP2L, KIF11, MKI67 and PLK1) that were positively and significantly related to RRM2 in almost all TCGA cancers." (PMID 35740608, 2022).
cancer (continued). "In addition, the cancer stemness score (RNAss) was negatively correlated with LAIR1 and VAMP8 and positively correlated with CKAP2L and SOX6, indicating that these hub genes are linked to tumor stemness-related characteristics." (PMID 41614933, 2026). "Although variable, every cancer cell line we tested expressed detectable CKAP2L protein, and we did not recognize any noticeable pattern in its expression." (PMID 39073037, 2024). "The most frequent genes were CKAP2L (Cytoskeleton Associated Protein 2 Like), NCAPH (Non-SMC Condensin I Complex Subunit H), and SGO2 (Shugoshin 2), which were the top differential genes in more than 50% of cancers." (PMID 38396175, 2024). "Interestingly, the relative differences in CKAP2L and CKAP2 protein levels between cell lines were almost identical, suggesting that the expression of two paralogues is likely to be co‐regulated in cancer cells." (PMID 39073037, 2024). "But there were no pan-cancer studies on CKAP2L, and its role in cancer immunotherapy is also unclear." (PMID 37225919, 2023). "Several proteins involved in cytoskeleton rearrangement such as actin, TNS3, KIF23, CKAP2L, NEDD9 and PLEC were also hyperphosphorylated, indicating the known regulatory role of AXL in promoting cancer cell migration/invasion and inducing epithelial-mesenchymal transition (EMT)." (PMID 34439388, 2021). "Notably, these studies in cancer cells, however, did not specifically investigate the defects during mitosis in CKAP2L‐depleted cells." (PMID 39073037, 2024). "However, one cannot rule out the possibility that CKAP2L may play roles other than regulation of the mitotic spindle and chromosome segregation in cancer cells." (PMID 39073037, 2024). "However, no studies have yet explored CKAP2L at the pan-cancer level." (PMID 37225919, 2023).
tumor (13 papers, 2019 to 2026). "CKAP2L is a mitotic spindle protein that has been previously shown to be overexpressed in some tumors and to be associated with tumor progression and patient prognosis." (PMID 37225919, 2023). "We found that CKAP2L expression linked negatively with Th1 cell infiltration and markedly positively with Th2 cell infiltration in 33 tumor types." (PMID 37225919, 2023). "The investigation of the common 68 proteins in The Human Protein Atlas database (; proteinatlas.org) revealed a similar association between tumor and normal tissues at the protein level for CKAP2L, AURKB, CDC25A, APIP, and LGALS3." (PMID 36529823, 2022). "Our immunohistochemical staining showed that levels of CKAP2L protein correlated with the mRNA levels and that CKAP2L upregulation was associated with higher tumor grades, which was consistent with the bioinformatics analysis of TCGA and the CGGA datasets." (PMID 33375517, 2020). "Analysis of genetic alterations showed that the alterations with the highest percentage of CKAP2L in tumors were amplification and mutation, and these genetic alterations may contribute to the high expression of CKAP2L in tumor tissues." (PMID 37225919, 2023). "Cytoskeleton-associated protein 2-like (CKAP2L), a cell cycle-related protein, is correlated to tumor progression in some tumors." (PMID 37225919, 2023). "Meanwhile, the average tumor weight of the shCKAP2L group was significantly lower than the shCtrl group, and the CKAP2L-OE group was more than that of the Vector group." (PMID 36090903, 2022). "Results indicated that CKAP2L silencing down regulated the expression of Ki-67 and cleaved caspase-3, which implied the reducing ability of tumor proliferation and significance increase in apoptotic cell death as well." (PMID 35715760, 2022). "Then, it was found that CKAP2L is significantly over-expression in tumor tissues and human cultured cells of ESCC." (PMID 36090903, 2022). "Consistent with the information in the database, CKAP2L expression was significantly increased in the tumor tissues (P < 0.05)." (PMID 36090903, 2022). "Next, to further elucidate the mechanism of the CKAP2L expression on tumor progression, KEGG enrichment analysis unveiled that the cell cycle pathway plays a vital role in the oncogenesis of ESCC." (PMID 36090903, 2022). "Compared with the shCtrl group, the tumor volume in the shCKAP2L group was obviously reduced, while the tumor volume in the CKAP2L-OE group was larger than in the Vector group." (PMID 36090903, 2022). "The expression of CKAP2L and proliferation marker Ki-67, were detected to verify the ability of tumor proliferation." (PMID 35715760, 2022). "The genes CCNA2, CKAP2L, NCAPG, and NUSAP1 were not only significantly up-regulated in PCa tissues, but also positively associated with higher Gleason score and tumor stage, implicating significant contributions to the pathogenesis of PCa." (PMID 33927744, 2021). "This implies that the genes were mainly expressed in the tumor cells, proving the clinical diagnostic value of CCNA2, CKAP2L, NCAPG, and NUSAP1 again." (PMID 33927744, 2021). "According to the published literature, little is known about the role of CKAP2L in tumor development and proliferation." (PMID 33927744, 2021). "By contrast, higher CKAP2L staining significantly correlated with tumor grade (p = 0.005), further confirming that CKAP2L expression is associated with higher tumor grade." (PMID 33375517, 2020). "Among the 701 TCGA samples, we found that CKAP2L expression correlated significantly (p < 0.0001) with tumor grade." (PMID 33375517, 2020). "In the invasion study, fewer siCKAP2L-expressing cells migrated through the transwell membranes, suggesting that CKAP2L suppression reduced the invasiveness of these tumor cells (p < 0.05)." (PMID 33375517, 2020). "Furthermore, CKAP2L is closely related to the tumor immune microenvironment and can be used as a biomarker to predict tumor immunotherapy." (PMID 37225919, 2023).